CD44 (CD44 molecule (IN blood group))
Diseases named in the same sentence as CD44 in open-access papers (continued):
Sharing a sentence is not in itself a finding about the gene and the disease.
cancer (continued). "Furthermore, in TILs, CD133+CD44+ cancer stem cells (CSCs) have the ability to impair the function of cytotoxic CD8+ T cells (CTLs) in TME by altering the expression of their programmed-death ligand 1 (PD-L1) receptor." (PMID 36980527, 2023). "Therefore, OTUB1 plays a critical role in stabilizing SLC7A11 and regulates CD44 (cancer stem cell marker)-mediated effects on ferroptosis to promote the development of human cancers." (PMID 37190313, 2023). "Thus, a large number of platforms with sensitive and specific properties, especially biosensors, have been developed to detect selectively CD44 aiming at cancer diagnosis applications and CTCs detection." (PMID 37754116, 2023). "In addition, CD44 is an important stem cell marker and a critical regulator of cancer cells, and it also participates in the regulation of myoblast behaviors during the process of embryogenesis." (PMID 37108043, 2023). "CSCs derived from multiple malignant tumors have shown high expression of CD44." (PMID 37175453, 2023). "Therefore, the establishment of each CD44v-specific mAb is essential to reveal the function and develop CD44-targeting cancer therapy." (PMID 37504249, 2023). "Sentani and colleagues reported that mixed type GC showed a characteristically expression of cancer stem cell-related molecules (CD44, CD133, and ALDH1), receptor tyrosine kinase molecules (EGFR, c-MET, and HER2), and chromosomal instability compared to pure type GC." (PMID 37950183, 2023). "CD44 is a non-kinase transmembrane glycoprotein that is highly expressed in metastasized tumors, while CD44 variants may play a role in the EMT and adaptive plasticity of cancer cells." (PMID 37940972, 2023). "SPP1 facilitated cancer cell chemoresistance via the activation of the CD44 receptor, PI3K/AKT signaling, and ATP-binding cassette (ABC) drug efflux transporter activity, and anti-SPP1 and anti-CD44 antibodies improved the sensitivity of cancer cells to cisplatin in a mouse model." (PMID 37190178, 2023). "Still, assessing CD44 expression is complicated because many variant CD44 isoforms can be expressed on cancer cells and some, but not all, have predictive value." (PMID 37005380, 2023). "Similarly, in vivo studies using zebrafish cancer cell xenograft models showed that the glycoprotein CD44 and the integrins αvβ3 and α5β1 are required for weak (CD44 and αvβ3) and strong (α5β1) interactions between CTCs and endothelial cells." (PMID 37215087, 2023). "CD44 may provide a new molecular target for cancer therapy and may also serve as a marker of poor prognosis in the cancer population." (PMID 37511335, 2023). "Multiple cell adhesion molecules and tight junction proteins that confer epithelial-like traits, such as plakoglobin, ICAM1, and CD44, have been identified to underlie the outperforming attributes of CTC clusters in cell survival, cancer stemness, and immune invasion." (PMID 36991428, 2023). "It is worthwhile to establish cancer-specific anti-CD44 mAbs using the CasMab method." (PMID 37185762, 2023). "HA-based nanogels loaded with antitumor drugs could be highly internalized by cancer cells overexpressing CD44 and have great inhibition of tumor growth and metastasis." (PMID 36750868, 2023). "Although CD44 expression is recognized as a definite independent prognostic factor in various cancers, CD44v isoforms have increasingly attracted attention due to their much more specific expression in cancer stem cells and their various functions via signaling transduction compared with CD44." (PMID 37835592, 2023). "However, cancer-associated fibroblast (CAF) markers CD140b and CD44 were found to be highly present in both naïve and yCD::UPRT gene-transduced cells, confirming their CAF character." (PMID 37629139, 2023). "CD44 is also known as a cell surface marker of cancer stem-like cells (CSCs) in various carcinomas." (PMID 37185762, 2023).
cancer (continued). "However, studies on cell lines showed that HA increased the expression of ABC transporters, but only in cancer cells overexpressing the CD44 protein." (PMID 36830841, 2023). "Furthermore, the results of the western blot analysis in these tumors validated that the expression levels of the cancer stemness markers CD44 and CD133 were decreased in the sh-ELF4 group." (PMID 37674363, 2023). "Moreover, we also confirmed that CD44 expression was relevant to the levels of immune cell infiltration in various types of cancer with ESTIMATE and CIBERSORT." (PMID 37117249, 2023). "Expression of CD44 by cancer cells was first checked by immunohistochemistry." (PMID 37398648, 2023). "Moreover, TANK expression was positively correlated with PD-L1, PD-1, and CD44 expression in various cancers." (PMID 37215097, 2023). "Overall, these results confirmed that CD44 is instrumental in TME remodeling for various cancers." (PMID 37117249, 2023). "Its reduced levels are associated with higher GC recurrence rates and enriched CD44+ cells, establishing a negative correlation between miR-328 and cancer development." (PMID 38455361, 2023). "Hence, cancer cells frequently express a large number of CD44 variations, particularly in the late stages of progression." (PMID 36289579, 2023). "Moreover, one of the most widely explored membrane-bound receptors involved in cancer cell adhesion, invasion, and metastasis is CD44, which regulates the glycolytic pathway in different carcinomas, hence cell proliferation." (PMID 37108498, 2023). "The delivery of cytochrome C and granzyme B was directed to overexpressed CD44 cancer cells, and the nanogels could be tracked by fluorescent emission." (PMID 38140012, 2023). "Just like HA-based biosensors, both reported platforms could also be used to detect CD44, making them suitable biosensors to detect CD44 biomarkers in cancer diagnostics." (PMID 37754116, 2023). "CD44 as a cancer stem cells antigen is abnormally expressed by carcinomas of epithelial origin." (PMID 36759786, 2023). "Thus, it can be concluded that chemoresistant cells are characterized by the accumulation of cancer stem cells and the increased expression of stemness (CD44, CD133, CD10, ALDH) and pluripotency (NANOG, BMI1, OCT4, SOX2) markers." (PMID 37453969, 2023). "Several studies have shown that CD44 is expressed on the surface of cancer stem cells, which may contribute to cancer beginning and development." (PMID 36671915, 2023). "Allowing for the recent advanced understanding of CD44 variant isoforms, we hypothesized that clinical significance of CD44V putatively representing cancer stemness properties may be different from CD44T." (PMID 37098074, 2023). "The CD44 pathway plays a role in the motility and migration of cancer cells, which could lead to metastasis." (PMID 37759706, 2023). "Cancer stem cells are supposed to be resistant to the various anti-cancer therapies and an obstacle against treatments, and stem cell biomarkers have been identified such as CD44, CD133, Ascl2, and Lgr5 in CRC." (PMID 37098074, 2023). "However, several phase I trials investigating CD44-targeted therapies showed limited clinical success in treating cancer, and the occurrence of severe side effects led to the termination of the project." (PMID 36936902, 2023). "The structural characterization of CD44 is an important task, because this receptor is involved in many physiological and pathological processes, including inflammation, immune response, and cancer progression." (PMID 37509083, 2023). "Indeed, the HA receptor, CD44, is a major cell adhesion receptor expressed in cancer and cancer stem cells, which facilitates cell–cell and cell–matrix interactions, proliferation, differentiation, invasion, and migration." (PMID 37107200, 2023). "The hyaluronan/CD44 axis also influences cancer cell survival and proliferation." (PMID 37958796, 2023).
cancer (continued). "Therefore, it can be considered an efficient multifunctional contrast agent platform for targeting CD44+-overexpressing cancer cells." (PMID 36934115, 2023). "In addition to the observed positive correlation between ELF4 or FUT9 and the cancer stemness-related markers CD44 and CD133, our immunohistochemistry results revealed a significant positive correlation between the expressions of ELF4 and FUT9." (PMID 37674363, 2023). "Combined with our finding that SNAI2 was strongly related to the expression of CD276, NRP1, and CD44 in many cancer types, we speculated that the potential association between SNAI2 and CD276, CD44, or NRP1 was promising for our further studies." (PMID 37251370, 2023). "Finally, CD44 is also implicated as a marker for the induction of cancer stem cell (CSC) phenotype and thus, the therapeutic resistance in various cancers." (PMID 36342580, 2023). "HA carboxyl groups were complexed to the carboxyl groups of indium 111-labeled polyamidoamine (PAMAM) dendrimers and amino groups of polyethyleneimine to develop an imaging probe for CD44-positive cancers, exploiting the capacity of HA to link these types of tumors." (PMID 36986728, 2023). "Thus, the HA-coated nanoparticles can target cancer stem cells by binding to activated CD44 and delivering drugs." (PMID 37107200, 2023). "These NCs had efficient anticancer properties in serving CD44 overexpressed cancer cells." (PMID 37560418, 2023). "Previous studies revealed that CD44 might be unnaturally expressed in several cancer types and play an essential role in cancer progression." (PMID 37117249, 2023). "Furthermore, we investigated the CD44 status in EpCam+ /CD45− CRC in the cancer patient cohorts following the idea of detecting cancer stem cells." (PMID 36100762, 2023). "Western blotting results revealed that TMZ-resistant U87MG-R cells highly expressed CYBB along with Nrf2, SOD2, and other epithelial–mesenchymal transition (EMT) markers, such as slug, vimentin, N-Cadherin, and CD44, in addition to the upregulation of cancer stemness marker CD133." (PMID 37175412, 2023). "Interestingly, CD44 accounts as a cancer stem cell marker individually or in combination with other markers such as CD24, CD133 and CD34." (PMID 37491225, 2023). "CD44 serves as a cell surface receptor for various extracellular matrix molecules, mainly hyaluronan, and messenger molecules, such as growth factors, and has important functions in normal and disease states, the predominant one being cancer." (PMID 37894408, 2023). "Given that cancer cells and cancer stem cells overexpress CD44, HA-based drug, and nucleotide delivery systems may be an effective treatment strategy." (PMID 36930869, 2023). "Furthermore, HSC-3 was selected because HNSCC was shown to be the second highest CD44-expressing cancer type in the Pan-Cancer Atlas." (PMID 37176118, 2023). "We compared morphological indexes of CD44+ CRC from 8 chemotherapy-naive cancer samples representing the true-positive samples and counting 79 cells with all 12 non-malignant afflicted samples including healthy cohort representing the true negative cohort and counting 80 cells." (PMID 36100762, 2023). "CD44 is also known as a stem cell marker of many cancer cells." (PMID 37760811, 2023). "Additionally, the binding of HA and CD44 provided active targeting to cancer cells overexpressing CD44 receptor." (PMID 38102651, 2023). "IHC results show that KYSE30 cancer cells in both static and dynamic cultures express CD44, but FFPE-ESCC samples express CD44 on only a select cell population within the tissue biospecimen which weights against cell areas that do not express antibody markers in a semi-quantitative relationship." (PMID 36671668, 2023). "Additionally, they demonstrated that γδ-T-EVs induced significant cell apoptosis and selectively targeted radioresistant CD44+/high cancer stem-like cells (CSCs)." (PMID 37242569, 2023).
cancer (continued). "Besides binding HA, these GAG-modified forms of CD44 can also bind growth factors impacting cellular proliferation in inflammation and cancer progression." (PMID 37762403, 2023). "However, in colon adenocarcinoma, DMP-1 binds and activates proMMP-9 and bridges MMP-9 to CD44, αvβ3 and αvβ5 integrins on the cell surface, enhancing cancer cell invasion and metastasis." (PMID 36765749, 2023). "CD44, and particularly the CD44v isoform, functions as a marker for cancer stem cells (CSCs) not only due to its unique expression on the cell surface, but also, and more significantly, because of its potent role in regulating various CSC properties, partly via EGFR-mediated pathways." (PMID 37958796, 2023). "In MGC-803gastric cancer cells, the splicing of CD44 was controlled by SRSF1." (PMID 38106992, 2023). "The authors suggest that CD44-positive cells could represent the cell origin of CCA cancer stem cells." (PMID 38247453, 2023). "CD44 expresses on different types of cells including cancer cells." (PMID 37298284, 2023). "Potential therapeutic strategies targeting CD44-positive tumors, effectively blocking CD44, might provide ample opportunities to overcome chemoresistance in various cancer types." (PMID 36831554, 2023). "CD44 was chosen because of its prevalence in pan‐cancer CSCs." (PMID 36925705, 2023). "CD44 antibodies are under thorough investigationin various cancers for their ability to detect progenitor cells in vivo but may not be suitable for use in vitro." (PMID 37647213, 2023). "Furthermore, IHC analysis indicated a marked decrease in the staining intensities of Ki-67 and CD44, markers of cellular proliferation and cancer stemness, respectively, under conditions of ACTN1 depletion." (PMID 38057867, 2023). "Indeed, BIWA-4 (bivatuzumab), an anti-CD44 antibody, is currently in preclinical trials for patients with head and neck tumors, indicating the interest in CD44 inhibition as a potential cancer therapy." (PMID 37445860, 2023). "And high CD44 expressing cancer cells were mostly resistant to drugs." (PMID 38041196, 2023). "Then, we evaluated the correlation with CD44 and the functional status in specific cancers." (PMID 37117249, 2023). "Similar to the behavior of before mentioned inflammation-associated rare cells, the CD44+ CRC also showed what we have referred to as multi-pathology association which, in consequence translates into a low specificity towards cancer." (PMID 36100762, 2023). "Remarkably, MIF-(CD74+CD44) signalling between hepatocytes and T/NK and macrophages, which mediates immunosuppressive effects that have previously been illustrated for promoting cancer progression." (PMID 36860314, 2023). "Additionally, drug resistance can be activated downstream of CD44 through the Stat3 pathway in several other carcinomas, including breast and ovarian cancer cells." (PMID 37958796, 2023). "Furthermore, SCEACono2 exhibited a unique characteristic that cytokeratin, vimentin as well as cancer stem cell markers (CD44, CD133, ALP and Oct3/4) were positive." (PMID 37949965, 2023). "Expression of CD44 is upregulated in numerous human cancers, positing a pro-tumorigenic role." (PMID 37174657, 2023). "CD44v6, a functional variant of CD44, was overexpressed on cancer cells located in the invasive front of colorectal cancer, and SPP1-expressing TAMs interacted with CD44v6-postive cancer cells, indicating the significance of SPP1/CD44v6 binding in cancer progression." (PMID 37190178, 2023). "CD44 can serve as an adverse prognostic marker among patients with cancer." (PMID 37461792, 2023). "CD44 is involved in invasion, drug resistance and metastasis in cancer." (PMID 37283735, 2023). "CD44 is an important cancer stem cell marker and a poor prognostic marker in various malignancies." (PMID 36831550, 2023). "It has also been proven that CD44 O-glycosylation status regulates cancer aggressiveness." (PMID 37110670, 2023).
cancer (continued). "To examine whether the crude extract and 1′-O-methyl-averantin inhibit expression of cancer stemness markers in CSC221 cells, we measured expression of mRNA encoding ALDH1, CD133, CD44, Lgr5, Msi-1, and EphB1." (PMID 36797277, 2023). "Previous research demonstrates that HA/CD44 is essential for cancer cell bone metastasis." (PMID 36906534, 2023). "Because cancer stem cells and matrix metalloproteinases play a key role in carcinogenesis, CD44, MMP-2, and MMP-9 may be the potential prognosticators for RCC." (PMID 36831550, 2023). "In addition, quantitative real-time PCR demonstrated an increase in the expression of cancer stem cell (CSC) marker CD44 after prolonged exposure to 300 μM DETANO." (PMID 36830680, 2023). "Similarly, CD44 standard isoform (CD44S), which is upregulated in cancer cells, was found to protect against anoikis, while CD44 depletion attenuated mammosphere formation in vitro." (PMID 37442876, 2023). "The presence of HA on the surface could specifically target the HA receptor (CD44)-overexpressed malignant cancer cells." (PMID 36987181, 2023). "High CD44 expression is correlated with CSC-like phenotypes; therefore, blockade of CD44 may prevent the progression of cancer and slow the process of metastasis, recurrence, and resistance to chemotherapeutic agents." (PMID 36831550, 2023). "CD44 has been studied as a marker of cancer stem-like cells (CSCs) in tumors." (PMID 37504249, 2023). "Similarly, a meta-analysis assessing the prognostic significance of cancer stem cell markers in ovarian cancer from 52 studies concluded that CD44 correlated with worse disease-free survival, as well as with chemotherapy resistance." (PMID 37958796, 2023). "The role of CD44, as a non-kinase receptor, has been extensively studied and has been linked to chemoresistance and CSCs in several types of cancer, including PDAC19." (PMID 37880235, 2023). "Extensive research was conducted on HA in targeting CD44 in various cancer cells." (PMID 36826291, 2023). "TGF-β, CD133, and CD44 from spheroids stimulate mesothelium to produce fibronectin for cancer cells adhesion, enhance attachment of floating cells to the epithelial surface, and stimulate secretion of metalloproteinase-9 (MMP-9) that supports mesothelial invasion." (PMID 37448521, 2023). "For this purpose, resveratrol not only acts as pro-apoptotic (caspase-3) but also induces its effect against inflammation (NF-kB), vascularisation (VEGF), and cancer stem cells (CD44, CD133, ALDH1), and also targets the β1-integrin/HIF-1α axis that is highly pronounced in CRC cells." (PMID 36902421, 2023). "Several studies on cancer vaccines loaded in HA were designed to target CD44." (PMID 36975676, 2023). "Several studies have shown that the SPP1/CD44 axis contribute to cancer chemoresistance in solid cancers, so the SPP1/CD44 axis may represent one of the most critical mechanisms for cell-to-cell communication between cancer cells and TAMs." (PMID 37190178, 2023). "Furthermore, FAM83D protein can also promote the expression of CD44 and CD44+ cancer stem cell malignancy through the MAPK, TGFβ, and Hippo signaling pathways." (PMID 37476189, 2023). "Furthermore, a treatment of TME-HCT-116 cells with 5-FU, resveratrol or both agents in combination, significantly down-regulated inflammation (p-NF-kB), vascularisation (VEGF) and cancer stem cell (CD44, CD133, ALDH1) expression." (PMID 36902421, 2023). "CD44 is a transmembrane glycoprotein that is highly expressed in a lot of cancers, including GBM." (PMID 37174724, 2023). "CD44 is a transmembrane receptor that is overexpressed on the surfaces of various cells, including those of pancreatic cancer, and is also involved in metastatic spread and cancer aggressiveness." (PMID 37241888, 2023). "The most prominent HA receptor is CD44, which is abundant in both inflammatory and cancer cells." (PMID 37568628, 2023).